BRCA2 (BRCA2 DNA repair associated)
Diseases named in the same sentence as BRCA2 in open-access papers (continued):
Sharing a sentence is not in itself a finding about the gene and the disease.
prostate carcinoma (continued). "P/LP/D status aggregated across BRCA2, ATM, NBN, and PALB2 was strongly associated with risk of overall prostate cancer (OR = 4.51; 95% CI = 2.18–9.33; P = 4.75 × 10−05) and metastatic disease (OR = 6.92; 95% CI = 2.34–20.49; P = 4.76 × 10−04)." (PMID 38014910, 2023). "In the case of prostate cancer, BRCA1 and BRCA2 mutations would lead to 8.6% and 15% cumulative risks respectively by age of 65 years." (PMID 38274092, 2023). "In a molecular analysis of 333 primary prostate cancers, the Cancer Genome Atlas (TCGA) study showed a 19% prevalence of alterations in several DNA repair genes, including BRCA2, BRCA1, ATM, CDK12, FANCD2, and RAD51C." (PMID 37240284, 2023). "Mutations of DNA damage repair genes including BRCA2, BRCA1, ATM, and/or mismatch repair (MMR) genes are associated with an increased incidence of prostate cancer." (PMID 37828628, 2023). "We applied our prostate cancer trained models to a cohort of 26 bladder cancer samples, which included one known case with deep BRCA2 deletion." (PMID 36914848, 2023). "c.5278-2del has been detected in colorectal cancer and intrahepatic cholangiocarcinoma while BRCA2 c.9253del has also been reported for prostate cancer." (PMID 37791908, 2023). "In men with BRCA1 and 2 mutations in aggressive prostate cancer, the role of HPC sub-genes plays an important role, and BRCA2 mutations are associated with an increased incidence of prostate cancer." (PMID 37298192, 2023). "Defective HR due to defects in BRCA1 or BRCA2 has led to the use of poly(adenosine diphosphate(ADP)-ribose) polymerase (PARP) inhibitors in prostate cancer therapy." (PMID 37095257, 2023). "Six of the eight germline BRCA2 carriers with somatic reversion mutations had canonical BRCA-associated cancer types, including breast (n = 4), ovarian (n = 1), and prostate cancers (n = 1)." (PMID 36418296, 2022). "A recent prospective study estimated the lifetime risk of developing prostate cancer to be 29% for BRCA1 and 60% for BRCA2 carriers." (PMID 34320204, 2022). "The incidence of prostate cancer is greater among BRCA mutation carriers; namely, 1.35-fold and 2.64-fold greater in BRCA1 and BRCA2 carriers, respectively." (PMID 36010882, 2022). "As previously discussed, individuals with a germline mutation in several genes (BRCA2, ATM, PALB2) are at increased risk for biochemical recurrence and prostate cancer-specific mortality." (PMID 35732815, 2022). "BRCA1/2 homozygous deletions are infrequent except in prostate cancer, where BRCA2 deletions have been reported at 2.6% frequency and accounted for 25% of BRCA1/2-altered cases." (PMID 35740616, 2022). "Yadav and colleagues observed increased somatic mutations of BRCA2, BRCA1, and ATM in AA prostate cancer." (PMID 36922933, 2022). "We evaluated the associations of the most recently developed breast and prostate cancer PRS with site-specific cancer risks in the largest case-control study of male BRCA1 and BRCA2 carriers available to date." (PMID 34320204, 2022). "Our findings showed that these PRS, developed using population-based data, are associated with breast and prostate cancer risks for male BRCA1 and BRCA2 carriers." (PMID 34320204, 2022). "Less OS data were reported for other tumors: 6 studies for BRCA2m compared with BRCA2 wt in prostate cancer with an HR of 1.9 (1.1–3.2) and 2 studies for BRCA1/2m compared with BRCA1/2 wt in pancreatic cancer with an HR of 1.5 (0.8–3.1)." (PMID 35909902, 2022). "The previous study has found that patients with primary prostate cancer have lower HRD scores, while patients with germline BRCA2 mutations have higher HRD scores." (PMID 35836192, 2022). "PRSPC was associated with prostate cancer risk for BRCA1 (OR = 1.73, 95% CI = 1.28 to 2.33) and BRCA2 (OR = 1.60, 95% CI = 1.34 to 1.91) carriers." (PMID 34320204, 2022). "The most commonly altered HRD-related gene in prostate cancer is BRCA2, with a prevalence of 5–6% at the germline level in mCRPC patients." (PMID 35836192, 2022).
prostate carcinoma (continued). "Germline BRCA1 and BRCA2 PVs increase the developing prostate cancer with a higher likelihood of aggressive disease for BRCA2 PV carriers." (PMID 35563100, 2022). "Germline mutations of DNA homologous recombination repair (HRR) genes, particularly BRCA2, are frequently found in advanced prostate cancers (PCs), and predict poor outcomes for conventional therapies." (PMID 36362213, 2022). "The phase I/II PETRA trial evaluated AZD5305 as monotherapy in patients with advanced metastatic breast, pancreatic, or prostate cancer with germline BRCA1, BRCA2, PALB2, or RAD51C mutations." (PMID 36010882, 2022). "ATM and CHEK2-associated cancers were D’Amico intermediate or high risk, comparable to our previously published BRCA2 and BRCAX prostate cancer cohort." (PMID 35892882, 2022). "We identified ancestry-linked germline and somatic mutation frequencies in DNA damage repair genes (BRCA1, BRCA2, APC, and ATM), as well as three novel prostate cancer–associated genes (CACNA2D2, SYNE1, and ADAMTS2)." (PMID 36922933, 2022). "TOPARP-A assessed anti-tumour activity of olaparib in a sporadic metastatic castration-resistant prostate cancer population, whilst TOPARP-B was conducted in a subset with known genomic background, specifically BRCA2 or ATM mutations." (PMID 36010882, 2022). "We assessed the associations of these PRS with breast and prostate cancer risks for male BRCA1 and BRCA2 pathogenic variant carriers." (PMID 34320204, 2022). "As for prostate cancer, the addition of the genes included in this review to BRCA1 and BRCA2 more than doubles the mutational burden in both germline and in somatic sample PVs (8.6% to 20.7% and 15.2% to 36.9%)." (PMID 35563100, 2022). "BRCA2 variants were the most prevalent at 5.3%, and variants in ATM, CHEK2, PALB2, BRCA1, and RAD51D were also more common among men with lethal prostate cancer." (PMID 36446039, 2022). "Of all the genes identified, only BRCA2 and ADAM28 have been previously classified as recurrently mutated drivers in prostate cancer." (PMID 36131292, 2022). "Among them, BRCA2 lesions are found in 12% of metastatic castration-resistant prostate cancers, but very rarely in primary prostate cancer." (PMID 36010882, 2022). "Prostate cancers with a germline BRCA2 PSV are associated with higher rates of lymph node involvement, metastases, and prostate cancer-specific death for both primary and metastatic cancers." (PMID 35715489, 2022). "Whole-exome and transcriptome profiling of 150 metastatic castration-resistant prostate cancer found that more than 19% of them have at least one mutation in BRCA1, BRCA2, ATM and CDK12." (PMID 36371386, 2022). "The majority of these studies (10 of 13) describe accounts of BRCA2-mutated MBC cases and highlight the significant familial risk and increased lifetime likelihood of developing MBC or prostate cancer in patients with BRCA2 alterations." (PMID 35804947, 2022). "After quality control, the analyses included 483 BRCA1 (33 breast and 70 prostate cancer cases) and 1318 BRCA2 (244 breast and 141 prostate cancer cases) carriers of European ancestry (available online)." (PMID 34320204, 2022). "Germline BRCA2-altered prostate cancer patients had the highest HRD scores, germline ATM-altered patients had intermediate scores and germline CHEK2-altered patients had the lowest scores." (PMID 35740616, 2022). "Patients with germline mutations in homologous DNA recombination repair (HRR) genes, such as BRCA1, BRCA2, ATM, PALB2, and CHEK2, are at a higher risk of prostate cancer development and usually have worse prognosis." (PMID 34884926, 2021).
prostate carcinoma (continued). "This is important as studies have shown that prostate cancer patients with certain errors in their genes, such as BRCA2 or BRCA1, are more likely to have worse disease and poorer outcome." (PMID 34830851, 2021). "Germline mutations in BRCA2 and BRCA1 are associated with increased incidence and aggressiveness of prostate cancer, and have been identified as biomarkers for platinum therapy and PARP inhibitors." (PMID 33625671, 2021). "Eleven genes previously associated with increased risk of prostate cancer (including ATM, BRCA2, and HOXB13) were identified along with ten new candidate genes." (PMID 33804961, 2021). "A recent meta-analysis revealed that the relative risk of prostate cancer is 1.35-fold and 2.64-fold in BRCA1 and BRCA2 carriers, respectively." (PMID 34356066, 2021). "Studies have demonstrated that men with Prostate Cancer (PCa) harboring BRCA2/BRCA1 genetic aberrations, are more likely to have worse disease and a poorer prognosis." (PMID 34830851, 2021). "The combination of prostate cancer and colon cancer share both genetic risk factors such as the BRCA1/BRCA2 mutation and dietary ones." (PMID 34556087, 2021). "For example, the prostate cancer risk by age 80 years at the 5th and 95th percentiles of the PRS varies from 7% to 26% for carriers of BRCA1 PVs and from 19% to 61% for carriers of BRCA2 PVs, respectively." (PMID 34298749, 2021). "Prostate cancer was also diagnosed earlier in this cohort (BRCA1: 58 y vs. BRCA2: 52 years) as compared to the general population at 67 years." (PMID 34575694, 2021). "It has been highlighted that BRCA1/2 mutation carriers present an increased risk for prostate cancer (3.4-fold in BRCA1, 8.6-fold in BRCA2)." (PMID 33484353, 2021). "Genetics of prostate cancer have shown population specific features, particularly related mutations in HOXB13, NBN, and CHEK2; however mutations in BRCA2, mismatch repair genes, BRCA1, and ATM appear to contribute to risk in many populations." (PMID 34503195, 2021). "Of all cancers diagnosed, BC was the most common (N = 26, 57.7%; 3 BRCA1 and 23 BRCA2; P < 0.001), followed by prostate cancer (N = 7, 15.6%; 3 BRCA1 and 4 BRCA2)." (PMID 34575694, 2021). "The patient with advanced castration-resistant prostate cancer with neuroendocrine differentiation was a 53-year-old man with a tumour harbouring duplication of exons 1–3 in ATR, as well as BRCA2 and TMPRSS2-ERG somatic tumour mutations." (PMID 34040174, 2021). "Our study has shown that breast and prostate cancers are commonly diagnosed cancers, particularly among BRCA2 carriers." (PMID 34575694, 2021). "The entire coding regions and intron/exon boundaries of BRCA1 and BRCA2 genes have been analyzed by next generation sequencing (NGS) in a total of 30 familial prostate cancer patients." (PMID 34242281, 2021). "The results from our study show that breast and prostate cancer are the most common type of cancers diagnosed, particularly in BRCA2 carriers, despite the larger proportion of BRCA1 carriers in our study cohort." (PMID 34575694, 2021). "Prostate cancer diagnosis was also earlier in BRCA2 carriers at 52 years compared to BRCA1 carriers at 58 years." (PMID 34575694, 2021). "A 2019 analysis of over 17,000 tumours, including 1042 prostate cancers, identified BRCA2 aberrations in 92 cases." (PMID 33106584, 2021). "The hereditary cancer working group from SEOM recommends prostate cancer screening with annual serum PSA measurements in male BRCA2 carriers starting at age 40, while this screening approach can also be offered to BRCA1 carriers." (PMID 32655641, 2020). "Shortly after the publication of our manuscript, Patel and coworkers proposed the existence of a prostate cancer cluster region (PCCR) at the 3′ end of BRCA2, based on retrospective cohort data." (PMID 32532514, 2020).
prostate carcinoma (continued). "A BRCA2 prostate cancer cluster region (PCCR) was recently proposed (c.7914 to 3′) wherein pathogenic variants (PVs) are associated with higher prostate cancer (PCa) risk than PVs elsewhere in the BRCA2 gene." (PMID 32532514, 2020). "In detail, two women had a first-degree relative, six women (one BRCA2 carrier) had a second-degree relative, while two women presented two first or second-degree relatives affected by prostate cancers." (PMID 32429297, 2020). "Mutations in DNA repair genes such as BRCA1, BRCA2, ATM, CHEK2, and PALB2 are of importance in prostate cancer." (PMID 32197306, 2020). "The prime example is using poly (ADP-ribose) polymerase (PARP) inhibitors for the treatment of adults with advanced breast, ovarian, and prostate cancers in the context of germline mutations in DDR genes, such as BRCA1, BRCA2, ATM, or PALB235–37." (PMID 32371905, 2020). "BRCA2-type HRD deficiencies (including BRCA2, RAD51C, PALB2 deficiencies) were more frequent in pancreatic and prostate cancer." (PMID 33149131, 2020). "Differentiation is made between BRCA1 and BRCA2 carriers based on the higher penetrance of prostate cancer in male BRCA2 carriers." (PMID 32655641, 2020). "The antitumour activity of olaparib indicated in this trial, in patients with metastatic castration-resistant prostate cancer with both germline and somatic aberrations of BRCA2, now supports the implementation of NGS testing of tumour samples." (PMID 31806540, 2020). "Prostate cancer in germline BRCA2 carriers appears to occur at an earlier age; has a more aggressive phenotype, a higher risk of nodal involvement, and distant metastasis; and is associated with a poor survival outcome in comparison to noncarriers." (PMID 32655641, 2020). "Germline mutations in the transcription factor HOXB13 and DNA damage repair genes such as BRCA1, BRCA2, CHEK2, as well as the mismatch repair (MMR) genes MSH6 and PMS2, have been shown to increase the risk of prostate cancer, the most common cancer among men." (PMID 32197306, 2020). "The Belgian Society of Human Genetics recommends annual prostate cancer screening with serum PSA and DRE for male BRCA1 and BRCA2 mutation carriers from the age of 40 onwards." (PMID 32655641, 2020). "Men with BRCA1/2 PV/LPVs should undergo clinical breast examination every 6–12 months, starting at the age of 35, and annual prostate cancer screening, starting at the age of 40 (in particular in BRCA2 PV/LPV carriers)." (PMID 32046255, 2020). "The application of PARP inhibitors in the treatment of prostate cancer was initiated in 2015 following the finding that 19.6% of prostate cancers had BRCA1, BRCA2 or ATM mutations." (PMID 33015058, 2020). "In previous studies on prostate cancer cells, PCAT-1 expression was found to cause functional impairment in homologous recombination with an inhibitory effect on BRCA2 tumor suppressor." (PMID 31319040, 2020). "The link between an elevated risk of prostate cancer and germline BRCA pathogenic variants has been well established, with the strongest association for BRCA2." (PMID 32655641, 2020). "Emerging data has also linked several germline DNA mutations to prostate cancer, namely BRCA1, BRCA2, MSH, ATM, PALB2, CHEK2, and MUTYH." (PMID 32957584, 2020). "Among candidate prostate cancer genes, PV frequencies were highest for BRCA2 (3.8%), ATM (2.7%), and CHEK2 (2.5%)." (PMID 32439974, 2020). "Evidence reported to date on the response of germline BRCA2-mutant prostatic cancers to standard treatments is conflicting." (PMID 31366128, 2019). "Olaparib treatment reduced AR levels only in BRCA2-knockdown prostate cancer cells, indicating that 6-TG and olaparib regulate AR through different molecular mechanisms, the first being BRCA2-independent and the second BRCA2-dependent." (PMID 31284411, 2019).
prostate carcinoma (continued). "Taken together, we have shown that Andrographolide is an effective anti-cancer compound for prostate cancer by regulating genes associated to double-strand breaks such as ATM, NBN, BRCA2 BLM, PALB2 and BLM." (PMID 30800220, 2019). "Our results show that treatment of castration-resistant prostate cancer cells with 6-TG significantly decreased AR levels, independently on BRCA2 expression." (PMID 31284411, 2019). "Germline and somatic aberrations in DNA damage repair (DDR) genes are more prevalent in prostate cancer than previously recognized, with BRCA2 as the most commonly altered gene." (PMID 30871108, 2019). "Instead, olaparib treatment reduced AR protein levels only in BRCA2-knockdown prostate cancer cells, and the addition of 6-TG had a synergic effect in reducing AR levels." (PMID 31284411, 2019). "BRCA2 and ATM mutated, as well as ETS-fusion-positive prostate cancers have the highest percentage of gains, while the majority of CDK12-mutant tumors do not have any change in ploidy." (PMID 31366128, 2019). "Prostate cancer patients who have mutations in the DNA repair pathway (such as BRCA1, BRCA2, ATM, RAD51D and PALB2) have been shown to be significantly more likely to have advanced disease than patients without these mutations." (PMID 31915536, 2019). "Germline BRCA2-mutant prostate cancers harbor a twofold higher percentage of genomic aletrations, graeter somatic single-nucleotide variant and increased CAN burden compared to localized sporadic prostate tumors." (PMID 31366128, 2019). "Transient overexpression of BRCA2 in prostate cancer cells resulted per se’ in decreased cell proliferation, increased apoptosis and resistance to 6-TG, PTX or a combination of them." (PMID 31284411, 2019). "Since the castration-resistant prostate cancer cells assayed in this study have decreased BRCA2 levels compared to the normal PNT1A cells, it is possible that reduced repair of 6-TG-induced DSBs by HR contributes to activation of apoptosis in cancer cells." (PMID 31284411, 2019). "We then investigated the effect of 6-TG alone and in combination with the taxane paclitaxel on normal immortalized and castration-resistant prostate cancer cells, and its dependence on BRCA2 expression." (PMID 31284411, 2019). "Pathogenic variants of high and moderate penetrance genes, such as BRCA1 and BRCA2, mismatch repair genes, and HOXB13 confer modest to high lifetime risk of prostate cancer." (PMID 31186630, 2019). "Taken together, these results demonstrate that BRCA2 levels modulate the sensitivity of prostate cancer cells to 6-TG to a similar extent as olaparib and that 6-TG treatment decreases the expression of AR independently on BRCA2." (PMID 31284411, 2019). "The effect of 6-TG treatment in BRCA2-knockdown prostate cancer cells before and after reconstitution of BRCA2 levels by ectopic expression was compared with treatment with olaparib, a Food and Drug Administration (FDA)-approved PARP inhibitor." (PMID 31284411, 2019). "Some, such as BRCA2, have emerging clinical relevance in the treatment and screening for prostate cancer." (PMID 31186630, 2019). "CNAs at the level of MYC, MYCN, GSK3B, MTOR, and BRCA2 are more frequently detected in germline BRCA2-mutant prostate cancers than in sporadic localized cancers." (PMID 31366128, 2019). "We show here that gain of BRCA2 expression in castration-resistant prostate cancer cells confers resistance to 6-TG- and olaparib-induced apoptosis but sensitivity to two 6-TG analogues, namely 2-N-6-BP and 2,6-DTP." (PMID 31284411, 2019). "PRI739, a BRCA2 E1308X carrier, was diagnosed at 53 and two first-degree relatives with a history of prostate cancer: his father was diagnosed at 70 years and a brother who died at 47 years." (PMID 30400234, 2018).